PRAME (PRAME nuclear receptor transcriptional regulator)
Diseases named in the same sentence as PRAME in open-access papers (continued):
Sharing a sentence is not in itself a finding about the gene and the disease.
melanoma (continued). "IHC has been able to elucidate many prognostic and predictive biomarkers including MART1/Ki-67, preferentially expressed antigen of melanoma (PRAME), makers of lymphovascular invasion (e.g., CD31/SOX-10) and mismatch repair (MMR) proteins, among many others." (PMID 37900283, 2023). "Gain- and loss-of-function studies as well as proteomics were employed to characterize the role of PRAME (preferentially expressed antigen in melanoma)." (PMID 37173882, 2023). "PRAME expression is used to support the diagnosis of melanoma over nevus in combination with histopathological features and other findings." (PMID 37796789, 2023). "Eleven clusters were annotated as tumor cells because they expressed high levels of melanoma-associated marker genes (MLANA, MITF, PRAME and SOX10)." (PMID 38065972, 2023). "Preferentially expressed antigen in melanoma (PRAME) belongs to the CTA gene family and was found to be abnormally expressed among different types of cancers." (PMID 36980687, 2023). "Considering the involvement of PRAME in tumorigenic processes, we suggest the use of a cut-off value of 100 cells/mm2 for melanoma diagnosis." (PMID 37047361, 2023). "PRAME (PReferentially expressed antigen in melanoma) is a cancer testis antigen found to be overexpressed in melanoma." (PMID 37877026, 2023). "Recently, a tape-strip test, Pigmented Lesion Assay (DermTech, La Jolla, CA), has been introduced that analyzes the RNA from the stratum corneum for expression levels of RNA Linc00518 (Linc) and PRAME, which are overexpressed in melanomas." (PMID 38076247, 2023). "In previous studies, PRAME has been identified as a useful biomarker and has received increased attention as an additional tool in the diagnosis of melanoma." (PMID 37047361, 2023). "PRAME expression also seems retained in primary dedifferentiated melanomas, but more studies are needed to confirm these findings." (PMID 37958863, 2023). "Gene expression profiling has revealed that the upregulation of PRAME in melanoma can be distinguished from benign melanocytic proliferation in clinical studies." (PMID 36910848, 2023). "Preferentially expressed antigen in melanoma (PRAME) expression was a significant prognostic marker in light tumors (P = 0.02) but not in dark tumors (P = 0.85)." (PMID 37193315, 2023). "High expression of PRAME is restricted to testis in adult tissues, while it is frequently augmented in malignant settings including melanoma or lung cancer, which adds PRAME to the family of cancer-testis antigens (CTAs)." (PMID 37173882, 2023). "Preferentially expressed antigen in melanoma (PRAME) is crucial for multiple cellular processes as well as immunotherapy response in human cancers among the cancer/testis antigen gene family." (PMID 38022619, 2023). "The PReferentially expressed Antigen in MElanoma (PRAME) protein has been shown to be an independent biomarker for increased risk of metastasis in Class 1 uveal melanomas (UM)." (PMID 37626310, 2023). "A pigmented lesion assay (PLA) is used to non-invasively detect the presence of three genes associated with melanoma (LINC00518, PRAME, and TERT) using adhesive patch testing and has the potential to reduce unnecessary biopsies." (PMID 36579219, 2022). "PRAME is expressed by melanoma and many different tumors: a higher expression is typical of advanced diseases and is associated with lymph node spread of the disease." (PMID 35328098, 2022). "Of the 127 cases of melanoma (superficial spreading, lentigo maligna, and pagetoid histotypes), PRAME was strongly positive in 104/127 cases (81.8%) with intensity 4+ and 3+." (PMID 36140597, 2022). "In 17 cases (13.3%; melanoma spindle and nevoid cell histotypes), PRAME was positive in percentage 2+ and with intensity ranging from 2+ to 3+." (PMID 36140597, 2022).
melanoma (continued). "PRAME (preferentially expressed antigen in melanoma) is a cancer testis antigen (CTA) that was first identified in 1997 through analysis of the specificity of tumor-reactive T-cell clones derived from a patient with metastatic cutaneous melanoma." (PMID 35328098, 2022). "The expression of PRAME was useful in distinguishing between melanomas and other melanocytic lesions of the nail." (PMID 35328098, 2022). "The preferentially expressed antigen of melanoma (PRAME) gene is recognized by human leucocyte antigen (HLA-24) located in the human chromosome of 22q11." (PMID 35788450, 2022). "First, we identified tumor cells by inferred large-scale CNVs from single-cell expression profiles and newly identified PMEL, S100B, SERPINE2, TYR, and PRAME as marker genes for melanoma malignant cells." (PMID 35646893, 2022). "In contrast, high levels of PRAME mRNA have been found in a number of different cancer indications, including melanoma, non-small cell lung cancer, multiple sarcoma subtypes, and epithelial ovarian cancer." (PMID 35454906, 2022). "Among melanoma subtypes, PRAME was diffusely expressed in 94.4% of acral melanomas, 92.5% of superficial spreading melanomas, 90% of nodular melanomas, 88.6% of lentigo maligna melanomas, and 35% of desmoplastic melanomas." (PMID 35328098, 2022). "To exclude that the clustering was affected by admixed brain-derived stromal cells, we calculated the tumor cell content based on the expression levels of PRAME (Preferentially Expressed Antigen in Melanoma) observed in melanoma cell lines." (PMID 36435874, 2022). "Diffuse nuclear immunoreactivity for PRAME was found in 87% of metastatic and 83.2% of primary melanomas." (PMID 35328098, 2022). "PRAME is a known transcriptional repressor protein, that is, expressed in human melanomas and recognized by cytolytic T lymphocytes." (PMID 35664317, 2022). "Another useful marker in such cases is preferentially expressed antigen in melanoma (PRAME), a newly used marker expressed in primary and metastatic melanoma but rarely in benign melanocytic lesions." (PMID 36289768, 2022). "Although diffuse PRAME immunoreactivity in melanocytic lesions is highly suggestive of CM, PRAME expression alone is insufficient for a conclusive melanoma diagnosis." (PMID 36547217, 2022). "Lezcano and colleagues (2018) performed an IHC analysis for preferentially expressed antigen in melanoma (PRAME) protein expression in melanocytic tumors and found that 83.2% of primary cutaneous melanomas regularly and diffusely expressed PRAME." (PMID 36547217, 2022). "Several markers were used including Melan-A/MART1, human melanoma black-45 (HMB-45) antigen, S-100 protein, p16, MiTF, and, relatively recently, the preferentially expressed antigen in melanoma (PRAME)." (PMID 36140597, 2022). "PRAME has been reported to be overexpressed in a variety of malignancies including malignant melanoma, showing an utility in distinguishing between benign and malignant lesions." (PMID 35484605, 2022). "The Preferentially Expressed Antigen in Melanoma (PRAME) is a highly relevant cancer/testis antigen for TCR-T immunotherapy due to broad expression in multiple solid cancer indications." (PMID 35454906, 2022). "A dose-escalation phase I/II study (NCT01149343) with recombinant PRAME protein with the AS15 immunostimulant in 66 patients with advanced PRAME-positive melanoma showed an acceptable safety profile and induction of humoral and cellular immune response." (PMID 35565234, 2022). "Primary research in cancer biology found PRAME to be a dominant repressor of the retinoic acid receptor (RAR) in melanoma cells." (PMID 35386283, 2022). "A relatively new marker molecule is PRAME (PReferentially expressed Antigen in MElanoma), an antigen that is expressed in multiple malignant tumors including MM." (PMID 35645230, 2022).
melanoma (continued). "CML cells express both leukemia-specific antigen derived from the BCR-ABL fusion protein and leukemia-associated antigens, including Wilms tumor 1(WT1), proteinase 3 (PR1), and preferentially expressed antigen of melanoma (PRAME)." (PMID 34771599, 2021). "This study highlights that PRAME expression in thin melanomas is lower and more heterogeneous than has been demonstrated for in situ and thicker melanomas." (PMID 34359765, 2021). "The melanoma-antigen family A proteins (MAGE-A), the Preferentially expressed Antigen in Melanoma (PRAME), and the New York esophageal squamous cell carcinoma 1 (NY-ESO-1) are amongst the principal targeted CTAs for cancer vaccines." (PMID 34681560, 2021). "Our findings are consistent with a prior study identifying PRAME protein expression in a portion of melanocytes in a minority of BN and DN and diffuse expression in melanoma cells in CMM." (PMID 35008167, 2021). "Preferentially expressed antigen in melanoma (PRAME) is a cancer/testis antigen (CTA) that is predominantly expressed in normal gametogenic tissues and a variety of tumors." (PMID 34074333, 2021). "We found that diffuse PRAME expression was highly specific but only moderately sensitive for thin melanomas." (PMID 34359765, 2021). "Our work, together with other studies on PRAME expression in melanocytic tumors, raises the question which PRAME threshold supports a melanoma diagnosis." (PMID 34359765, 2021). "A decrease in the number of natural killer (NK) cells and cytotoxic T-lymphocytes (CTLs), and impaired responses to leukemia-associated antigens WT1, proteinase 3, BMI-1, and preferentially expressed antigen of melanoma (PRAME) were observed at diagnosis." (PMID 34771599, 2021). "The aim of our study was to answer these unresolved questions by investigating PRAME expression in thin melanomas (≤1.00 mm) and SDN including ambiguous melanocytic tumors with long-term follow-up in a real-world setting." (PMID 34359765, 2021). "Here, we show that diffuse PRAME expression in superficial atypical melanocytic proliferations is highly specific for melanomas." (PMID 34359765, 2021). "The myPath Melanoma Test utilizes the expression of 14 signature genes, including PRAME, CXCL9, CXCL10, S100A7, S100A8, and S100A9, and nine reference genes to distinguish BN from CMM." (PMID 35008167, 2021). "PRAME was originally described in melanoma cell lines as a tumor antigen recognized by autologous cytotoxic T cells." (PMID 34359765, 2021). "Most melanomas (67.6%) showed uniform PRAME expression in the in situ and invasive component, whereas most SDN (81.0%) showed a decreasing gradient with depth." (PMID 34359765, 2021). "Although PRAME expression is frequently detected in melanomas, certain subtypes, including desmoplastic melanomas, show a lower frequency of this gene expression, limiting the use of PLA for the detection of these melanomas." (PMID 34683091, 2021). "PRAME is found to be overexpressed in melanomas, acute leukemia cells, various sarcomas, breast cancer, cervical cancer, lung cancer, melanomas, and ovarian cancers among others." (PMID 34681560, 2021). "Of 68 melanomas with PRAME immunoreactivity, 67.6% showed equal PRAME expression in the epidermal and dermal portion and most remaining melanomas (29.4%) weaker dermal expression." (PMID 34359765, 2021). "Preferentially expressed antigen in melanoma (PRAME) is one of the most immunogenic CTAs discovered to date." (PMID 33381588, 2020). "Levels of expression of GAGE, NY-ESO1, MAGEA1, PASD1, PRAME in melanoma cell lines were significantly higher than in STBS group (adj." (PMID 32042403, 2020). "Numerous studies have demonstrated that preferentially expressed antigen in melanoma (PRAME) is abnormally expressed in various solid tumours." (PMID 33381588, 2020). "To gain a more detailed understanding of what happens during a read jumble event, we examined the PReferentially expressed Antigen of MElanoma (PRAME) gene family." (PMID 33126848, 2020).
melanoma (continued). "PRAME (preferential expressed antigen in melanoma) is a member of the cancer testis antigen family that has normal expression in the testis, ovaries, adrenals, endometrium, and placenta." (PMID 33339193, 2020). "Among them, two genes, preferentially expressed antigen in melanoma (PRAME) and Janus kinase and microtubule interacting protein 1 (JAKMIP1), were reported as cancer/testis (CT) genes that were selectively expressed in testis and cancers." (PMID 32732980, 2020). "This is the case for the large PRAME (preferentially expressed antigen in melanoma) family, which have more than 80 paralogs in mouse and <2 processed pseudogenes per parent." (PMID 32728065, 2020). "The antigen PRAME (preferentially expressed antigen of melanoma) was initially identified in two melanoma cell lines and was described to be overexpressed in a large fraction of different tumors and leukemias." (PMID 30897713, 2019). "PRAME (preferentially expressed antigen in melanoma) expression is elevated in ALL and other malignancies." (PMID 29977016, 2019). "PRAME or PReferentially expressed Antigen in Melanoma is a testis-selective cancer testis antigen (CTA) with restricted expression in somatic tissues and re-expression in various cancers." (PMID 31311081, 2019). "Expression of a cancer-testis antigen called PRAME (preferentially expressed antigen in melanoma) has been shown to increase metastatic risks in both low-risk and high-risk melanomas." (PMID 29755733, 2018). "Another study found that the overexpression of preferentially expressed antigen of melanoma (PRAME) induces the repression of three genes: Hsp27, S100A4 and p21." (PMID 28903396, 2017). "Overexpression of PRAME is also common in solid malignancies, particularly melanoma and nephroblastoma." (PMID 29029482, 2017). "Preferentially Expressed Antigen in Melanoma (PRAME) is a cancer/testis antigen initially isolated from melanoma cells." (PMID 29029482, 2017). "A dose-escalation phase I/II study (NCT01149343) assessed the safety, immunogenicity and clinical activity of the PRAME immunotherapeutic (recombinant PRAME protein (recPRAME) with the AS15 immunostimulant) in patients with advanced melanoma." (PMID 27843625, 2016). "In this study, we examined the role of preferentially expressed antigen of melanoma (PRAME) in lung cancer metastasis." (PMID 27391090, 2016). "PRAME (Preferentially expressed antigen of melanoma) was first isolated as a human melanoma antigen recognized by Cytotoxic T cells (CTL)." (PMID 27275197, 2015). "Recently, preferentially expressed antigen in melanoma (PRAME) has been described as a tumor antigen and is overexpressed in a variety of cancers." (PMID 26451736, 2015). "This gene expression signature also contributes additional molecular information by assessing the gene expression of PRAME, a known melanoma tumor antigen." (PMID 25727210, 2015). "We investigated four CT antigen families with dynamic expression profiles in human: Preferentially Expressed Antigen in Melanoma (PRAME), Synovial Sarcoma X breakpoint (SSX), Melanoma antigen family A (MAGEA) and G-antigen (GAGE)." (PMID 25089626, 2014). "In melanoma cells, PRAME functions as a repressor of retinoic acid (RA) signaling through the interaction with RA receptors (RARs) and recruitment of polycomb proteins." (PMID 23565261, 2013). "PRAME (preferentially antigen expressed in melanoma) was identified as a tumor antigen recognized by autologous tumor-specific cytotoxic T lymphocytes from a patient with melanoma." (PMID 23409080, 2013). "Preferentially expressed antigen in melanoma (PRAME) is a member of the CTAs, and was originally identified as a tumor antigen expressed in melanoma cells, triggering an autologous cytotoxic T cell-mediated immune response." (PMID 23565261, 2013).
melanoma (continued). "The human tumour antigen PRAME (preferentially expressed antigen in melanoma) is frequently overexpressed during oncogenesis, and high PRAME levels are associated with poor clinical outcome in a variety of cancers." (PMID 22912744, 2012). "Among the nine recurrently hypo-methylated and over-expressed genes was the gene “preferentially expressed antigen in melanoma” (PRAME, 11/19 cell lines), which is over-expressed and a prognostic marker for clinical outcome in various types of cancers." (PMID 23144859, 2012). "The human oncoprotein PRAME (preferentially expressed antigen in melanoma) was first identified and cloned as the antigen responsible for an anti-tumour immune response in a melanoma patient." (PMID 22912744, 2012). "The preferentially expressed antigen of melanoma (PRAME) gene is involved in the regulation of cell death or cell cycle." (PMID 23023193, 2012). "The human tumor antigen PRAME (PRreferentially expressed Antigen in MElanoma) and HACE1 (HECT domain and Ankyrin repeat containing E3 ubiquitin-protein ligase) were both recently identified as a co-repressors of RAR signaling." (PMID 21949683, 2011). "Other genes were identified that show similarity to known gene families which play integral roles in DNA damage response and replication, namely, SWI/SNF, arp2 (actin related protein 2) and PRAME (PReferentially expressed Antigen of MElanoma)." (PMID 20454618, 2010). "In line with these genes, a gene called preferentially expressed antigen in melanoma (PRAME) was also scored in LNCaP and C4-2." (PMID 20021671, 2009). "Members of the preferentially expressed antigen of melanoma (PRAME) gene family made up the third largest gene family with mouse specific expansions." (PMID 19468303, 2009). "The protein PRAME was first detected as a tumour antigen in cells isolated from a melanoma, and high PRAME expression has been detected in 88–95% of primary melanomas." (PMID 18648365, 2008). "The tumour antigen PReferentially expressed Antigen of MElanoma (PRAME) is expressed in a variety of malignancies, including breast cancer." (PMID 18648365, 2008). "The expression of preferentially expressed antigen of melanoma (PRAME) has been detected in a variety of cancers including breast cancer, but its expression is low or absent in normal tissues." (PMID 18648365, 2008). "We performed an in-depth evolutionary analysis of a region of chromosome 1, which is copy number polymorphic among humans, and that contains at least 32 PRAME (Preferentially expressed antigen of melanoma) genes and pseudogenes." (PMID 16159394, 2005). "We identified a number of overexpressed genes previously associated with ovarian and other cancers including VEGF, osteopontin (OP), preferentially expressed antigen in melanoma (PRAME), TACSD2 (or GA733-1) and prostasin (PRSS8)." (PMID 14760385, 2004). "PRAME immunostaining shows high specificity for melanoma and melanoma in situ." (PMID 41835772, 2026). "Additionally, recent evidence highlights the utility of PRAME as an immunohistochemical marker to distinguish CCS from melanoma and other neoplasms." (PMID 40004764, 2025). "The vast majority of primary and metastatic cutaneous melanomas express PRAME, though exceptions may arise, particularly in desmoplastic melanomas." (PMID 39625060, 2025). "PRAME has emerged as a diagnostically and therapeutically relevant biomarker in melanoma." (PMID 40868240, 2025). "PRAME is also expressed in melanomain situ cases and can aid the early diagnosis of melanoma." (PMID 40507250, 2025). "PRAME expression is typically diffuse and strong in melanoma." (PMID 41426734, 2025). "From an immunohistochemical point of view, S-100 protein, HMB-45, Melan-A, SOX-10, and MiTF are usually positive (melanocytic line differentiation features) and recently also it was demonstrated the potential utility of negativity for PRAME in the differential diagnosis with melanoma." (PMID 40004764, 2025).